TNF (tumor necrosis factor)
Diseases named in the same sentence as TNF in open-access papers (continued):
Sharing a sentence is not in itself a finding about the gene and the disease.
amyloidosis (65 papers, 2011 to 2026). A disorder characterized by the localized or diffuse accumulation of amyloid protein in various anatomic sites. "A chronic state of inflammation caused by cytokines like IL-6, IL-18, and TNF-α represents a major link to the formation of increased amyloid plaques and tau tangles." (PMID 41280310, 2025). "TNF-α promotes synaptic loss and excitotoxicity and exacerbates amyloidosis, with heightened levels of serum TNF-α already identified in AD." (PMID 38891941, 2024). "Tocilizumab effects over proteinuria in FMF-associated amyloidosis has been analyzed in two series of 11 and 12 patients resistant to colchicine, anti–IL-1, or anti-TNF agents, in whom the previous colchicine therapy was maintained." (PMID 32655539, 2020). "This was associated with a reduced CXCL1, IL-1β, TNF-α-level and microgliosis, which correlated with amyloid deposition and total Aβ." (PMID 30872722, 2019). "In support of this idea, a recent study demonstrates that inhibition of TNFα signaling prevents pre-plaque amyloid-associated neuropathology and reduces plaque accumulation and tau phosphorylation in transgenic mouse models of AD." (PMID 28746336, 2017). "The reasons for switching from infliximab to another anti-TNF were ongoing underlying disease activity (n = 5), worsening of amyloidosis (n = 4), anaphylaxis (n = 4), aspergilloma (n = 1), and jugular and subclavian thrombosis (n = 1)." (PMID 28834898, 2017). "Inhibiting TNFα ameliorates amyloid-associated pathology, prevents the progressive loss of neurons and at last improves cognitive deficits in AD." (PMID 23405115, 2013). "Regarding the mechanism of inflammation in amyloidosis, pro-inflammatory cytokines such as IL-1β, IL-6, and TNF-α are associated with the formation of amyloid plaques, and these cytokines are proposed to trigger inflammatory responses and promote tissue damage." (PMID 40571902, 2025). "TNF can also upregulate the expression of IL-1, thereby increasing the production of precursor substances essential for the formation of amyloid plaques, neurofibrillary tangles, and Lewy bodies." (PMID 41586222, 2025). "In patient 3, who was unresponsive to multiple anti-TNF drugs, satisfactory results both in controlling disease activity of PsA and amyloidosis were achieved with high dose secukinumab treatment." (PMID 36128216, 2022). "Accordingly, CNS TNF-α inhibition with the intracerebroventricular injection of a TNF-α antibody, and peripheral TNF-α modulation significantly reduced tau phosphorylation in a mouse models of amyloidosis." (PMID 34972522, 2021). "In the current model, we focused on the prevention of gastrointestinal amyloidosis using neutralizing antibodies against inflammatory cytokines TNF-α and IL-1α/β; however, amyloidosis was partially ameliorated in both groups." (PMID 35008464, 2021). "KCASP1Tg mice were treated with neutralizing antibodies against TNF-α or IL-1α/β to prevent gastrointestinal amyloidosis, and amyloidosis was partially ameliorated." (PMID 35008464, 2021). "Tocilizumab (anti–IL-6 agent) has been successful in controlling disease activity and improving proteinuria in patients with FMF-associated amyloidosis and also in few TRAPS and HIDS/MKD patients resistant to anti-TNF and/or anti–IL-1 agents." (PMID 32655539, 2020). "In the present study, we investigated the role of TNF-α in the development of the amyloid phenotype in an AD mouse model by modulating the 3′UTR of the endogenous mouse gene." (PMID 32457323, 2020). "Taken together, biological strategies that block specific immune mediators such us TNF-α or IL-1β are effective in suppressing the disease activity, preventing reactive amyloidosis, and halting the progression of organ damage." (PMID 32380704, 2020). "Preclinical studies have shown that selective anti-TNF biologic, XPro1595, ameliorates neurologic dysfunction in mouse models of amyloid pathology." (PMID 33343293, 2020).
amyloidosis (continued). "In amyloid-burdened brain areas detrimental pro-inflammatory cytokines such as TNF-α, IFN-γ and IL-1β are likely to be the culprit." (PMID 31120951, 2019). "Inhibiting TNF-α signaling before amyloidosis further prevents the development of synaptic deficits in an AD mouse model." (PMID 31160541, 2019). "It is widely accepted that TNF-α exerts effects by inducing Aβ production in vitro and mediating toxicity induced by amyloidosis." (PMID 31039131, 2019). "Inhibition of TNF alpha decrease amyloid plaques and tau phosphorylation in the mouse brain, and so risk of AD, and this protein involved in the pathophysiology of NAFLD." (PMID 29564062, 2018). "The production of the precursor to SAA is the main step in the pathogenesis of amyloidosis, which is produced by inflammatory signals, IL-1β, tumor necrosis factor (TNF)-α, and IL-6." (PMID 27590627, 2016). "Interleukins and TNFα are critical cytokines in potentiating this immune response and are upregulated in settings of amyloid pathology; thus, we assessed their expression in Myd88−/− neuronal cultures." (PMID 25879763, 2015). "IL-6 and TNF-α, which are representative pro-inflammatory cytokines, were found to be induced in reactive astrocytes surrounding beta-amyloid deposits detected in 14-month-old Tg2576 mice." (PMID 24586443, 2014). "Etanercept has shown encouraging results in reduction of serum amyloid A in amyloidosis and patients with a baseline serum creatinine below 2 mg/dl tended to show a benefit following TNF-alpha inhibition." (PMID 23557013, 2013). "TNFα seems to be a critical mediator of the effects of neuroinflammation on early (pre-plaque) pathology in 3xTgAD mice, and its inhibition in the CNS may slow the appearance of amyloid-associated pathology, cognitive deficits, and potentially the progressive loss of neurons in AD." (PMID 21699726, 2011). "In addition, peripheral TNF-α modulates amyloid pathology by regulating blood-derived immune cell trafficking into the brain in double-transgenic mice with combined amyloid pathology and human TNF-α overexpression." (PMID 38397814, 2024). "The first research conducted in 2003 in Turkey assessed whether the rs1800629 TNF-α (−308G/A) and SAA1.1 polymorphisms play a role in progression of amyloidosis in FMF patients." (PMID 39132307, 2024). "In AD, elevated levels of tumor necrosis factor-α (TNF-α) may play a significant role in exacerbating amyloidosis, and IGF-1 attenuate amyloidosis by antagonizing TNF-α." (PMID 36691085, 2023). "Notably, the Ch− diet resulted in lower plasma choline and ACh, and elevated TNFα at 7 months, an age when amyloidosis commences in 3xTg-AD mice, but prior to NFT pathology." (PMID 37548694, 2023). "Scutellarin also demonstrated anti-amyloidosis effects, lower levels of proinflammatory cytokines, including tumor necrosis factor (TNF)-α and interleukin (IL)-6, and decreased levels of proinflammatory cytokines, soluble and insoluble Aβ in the brain and bloodstream of mice." (PMID 36678547, 2022). "Taken together, there is a possibility that the treatment with PCO causes elevation of HDL-C and enhancement of HDL functionality to induce the reduction of oxidized species (4-HNE and iNOS), inflammatory cytokines (IL-1β, IL-6, and TNF-α), and amyloid plaque size." (PMID 34439569, 2021). "In addition, TNFα along with monocyte chemoattractant protein were also shown to be increased before amyloid plaque deposition in the entorhinal cortex of 3xTgAD mice, another mouse model of AD." (PMID 30135948, 2018). "We have recently shown that in the TgCRND8 transgenic AD mouse model, increased hippocampal levels of the pro-inflammatory cytokine tumor necrosis factor alpha (TNFα) and enhanced excitatory synaptic transmission were early-onset changes that occurred weeks before amyloid plaque formation." (PMID 30135948, 2018). "In conclusion, increased levels of TNFα may be a potential early-stage biomarker in TgCRND8 mice before amyloid plaque formation." (PMID 30135948, 2018).
amyloidosis (continued). "Knocking out TNF signaling or more severe reductions in TNFα protein with high dose inhibitors may reduce amyloid pathology but at the expense of the immune system or cognitive function." (PMID 26436670, 2015). "High TNF-α levels during aging and in AD may contribute to amyloidosis." (PMID 35392832, 2022). "To assess whether the increased amyloid plaque burden resulted in an exacerbation of pro-inflammatory responses, we measured levels of the inflammation-associated molecules CXCL1, CCL3, IL-33, TNFα, IL-6, and IL-1β by multiplexed MSD ELISA." (PMID 32943069, 2020). "On the basis of these cases, however, anti-TNF agents seem to be an option for patients with FMF who are unresponsive or intolerant to colchicine therapy and might have a promising role in the treatment of FMF-associated amyloidosis." (PMID 23970817, 2013). "In this regard, further studies are recommended in order to precisely evaluate the efficacy and safety of anti-TNF-α and anti-IL-6 drugs in the management of FMF severity and complications, mainly amyloidosis, among children." (PMID 39132307, 2024). "Following amyloid plaque deposition, the activation of microglia and the release of inflammatory cytokines, including IL1β, IL6 and tumor necrosis factor alpha (TNF-α), have been documented in AD." (PMID 32707949, 2020). "There are few reports on the effect of anti-TNF and anti-IL-6 treatment on SAA concentration, dealing mostly with patients with amyloidosis, secondary to RA." (PMID 25525305, 2014). "In the present study, we further demonstrated that inhibition of TNFα by thalidomide administration lowers BACE1 levels and activity and therefore ameliorates amyloid pathology." (PMID 23405115, 2013). "Overall, the BBB-penetrating TNF-α inhibitor had better therapeutic indices than etanercept, a non-BBB-penetrating TNF-α inhibitor expected to modulate only peripheral but not CNS TNF-α, in the mouse model of amyloidosis." (PMID 34972522, 2021). "Our previous work showed that this BBB-penetrating TNF-α inhibitor reduces Aβ plaques, insoluble Aβ1-42, BBB-disruption, brain endothelial activation, and cognitive memory deficits in the APP/PS1 double transgenic AD mouse model of amyloidosis." (PMID 34972522, 2021). "Since we found a significant induction of IFITM3 in response to various inflammatory stressors (LPS, TNFα, and IFNγ) and recent findings suggest a novel role of IFITM3 in amyloid pathology, we sought to examine whether amyloid peptide could induce IFITM3 expression in primary microglia." (PMID 36012150, 2022). "Inflammatory cytokines, including interleukin (IL) 1β, IL6 and tumor necrosis factor-alpha (TNF-α), are involved in local inflammation triggered by amyloid plaque deposition and may induce neurotoxicity when produced chronically, favoring the generation of Aβ peptides." (PMID 32283734, 2020). "Our interpretation is that amyloid-driven IL-1β/TNF-α expression is not functional in tgHpaSwe." (PMID 30872722, 2019). "Indeed, neither Aβ nor βCTF, which have been previously suggested as possible TNFα inducers during the prodromal stage of amyloid pathology, were detectable in the present study." (PMID 27672476, 2016).
Splenomegaly (64 papers, 2007 to 2026). Abnormal increased size of the spleen. "Conversely, resistant WK ducks still exhibited significant weight loss, splenomegaly, histopathological damage, systemic iron accumulation, and TNFα-dominated immunity with reduced IgM." (PMID 40718811, 2025). "Regarding the alterations in the cytokine levels during malaria infection, TNF-α was described as a cytokine associated with splenomegaly in mice during the blood stage of malaria infection." (PMID 37628675, 2023). "Systematic treatment of CT-26 tumor-bearing mice with 5 × 106 CFU of SL7207 elevated blood TNF-α levels, caused splenomegaly, and resulted in weight loss of approximately 10%." (PMID 36986850, 2023). "However, Pg induced weight loss and systemic inflammation, such as splenomegaly and increased IL‐1β and TNF‐α levels in plasma, whereas Pg OMVs had minimal impact." (PMID 39932228, 2025). "Previous studies have also found an association between splenomegaly and IL-6 and TNF-α." (PMID 39364261, 2024). "Thus, systemic inflammation (e.g., high levels of IL-6 and TNF-α) is associated with splenomegaly in LPS-treated mice." (PMID 37491335, 2023). "This compound also showed preferable anti-inflammatory activity in vivo, including alleviating significantly gastric distention and splenomegaly caused by LPS stimulation, reducing the level of oxidative stress induced by LPS, and inhibiting the expression of IL-6 and TNF-α in serum." (PMID 37325874, 2023). "Taking together T-cell-derived IFN-γ play a prominent role in IL-15 mediated toxicityRegarding splenomegaly and hepatomegaly other cytokines induced by IL-15 like TNF-α or IL-18 might also be implicated." (PMID 27356750, 2016). "Further correlation analysis showed that TNF-α, which was correlated with splenomegaly, was significantly negatively correlated with Th2 cytokines and body weight gain." (PMID 40718811, 2025). "Hyperforin significantly inhibited imiquimod-induced splenomegaly, reduced serum levels of TNF-α and IL-6, and IL-17A in splenocytes and draining lymph nodes." (PMID 34025642, 2021). "The 3xTg mice displayed splenomegaly, hepatomegaly, elevated levels of pro-inflammatory markers, such as TNF-α and decreased lymphocyte population in spleen, which indicates a severe manifestation of systemic autoimmune/inflammatory responses." (PMID 34199639, 2021). "In this scenario, interfering with FAK led to a reduced tumor-dependent splenomegaly in mice and blunted the tumor necrosis factor α (TNFα)-dependent secretion of proinflammatory cytokines in 4T1 cells." (PMID 33562737, 2021). "GD patients affected with the most common visceral form of the disease have splenomegaly, hepatomegaly, bone lesions, cytopenia and chronic inflammation with elevated levels of IL-1, IL-6, IL-8 and TNF-α." (PMID 32872203, 2020). "During VL, splenomegaly is characterised by white pulp hyperplasia and IFNγ- and TNF-mediated killing of marginal zone macrophages, resulting in dysregulated lymphocyte trafficking." (PMID 33049000, 2020). "MRL/lpr mice possessed a lean phenotype despite exhibiting severe splenomegaly, lymphadenopathy, systemic inflammatory status markers (supported by high serum TNF-α), and lymphocytic infiltration in the fat." (PMID 32686763, 2020). "IL6 and TNFα were found elevated in the serum of β−/− mice and splenomegaly was observed at 16 weeks of age33,34." (PMID 29849099, 2018). "The early acute infection of C57BL/6 or BALB/c mice with P. chabaudi (AS) is accompanied by splenomegaly, and a large but transient inflammatory response comprising elevated levels of cytokines such as IL-12, TNF-α, IL-6, and IFN-γ." (PMID 17555592, 2007). "Our study extended previous findings by showing that splenomegaly and elevated serum levels of IL-1β and TNF-α in LPS models could be rescued by PDA NPs treatment." (PMID 36765377, 2023).
Splenomegaly (continued). "This notion is supported by a study of CII-immunization in TNF deficient mice, which reported the development of splenomegaly, increased splenic memory CD4+ T cells, but not B cells, and impaired IgG class switching in comparison to wt CII-immunized mice." (PMID 35216345, 2022). "Indeed, the absence of RELMα led to increased circulating inflammatory cytokines including TNFα, IFNγ, IL-6 and IL-1α, and exacerbated splenomegaly." (PMID 34349768, 2021). "However, in vivo neutralization of TNF-α did not exacerbate susceptibility to colonization or splenomegaly in mice neutralized of γδ T cells, indicating TNF-α is required for γδ T cell-mediated protection against B. abortus." (PMID 21765931, 2011). "In our murine model, we observed acute splenomegaly as well as significantly elevated IFN-γ, TNF, and IL-6 in the circulation of TAS2010-vaccinated mice." (PMID 37733817, 2023). "Mice injected with D. andersoni EVs and F. tularensis had also lessened splenomegaly and decreased levels of interferon (IFN)-γ and tumor necrosis factor (TNF)-α in the blood." (PMID 34140472, 2021). "However, our new method leads to considerably reduced systemic inflammatory reactions in the animals, as indicated by the moderate splenomegaly and weight loss, as well as little or no significant increase of IL-1β, TNF-α and IFN-α concentrations in the blood of the animals." (PMID 30842501, 2019). "This therapeutic efficacy was accompanied by the alleviation of splenomegaly and a systemic reduction in inflammatory cytokines (IL-17 and TNF-α) without inducing hepatotoxicity." (PMID 41782885, 2026). "Therefore, we examined the serum levels of the pro-inflammatory cytokines IL-1β, IL-6, and TNF-α in NCI-H460 xenograft model, which has the best response to GLPs in terms of tumor and splenomegaly inhibition." (PMID 36185644, 2022). "In previous studies, several cytokines, such as SCF, TNF-α, PDGF, TGF-β, bFGF, PF4, and IL-8 contributed to the expansion of malignant clones from the BM to the spleen as an EMH site, leading to the development of splenomegaly in MF patients." (PMID 29562644, 2018). "In addition, splenomegaly and hypotension were more prevalent in patients with high SOD-1 and TNF-alpha levels compared to those with low levels of both factors (43.2% vs. 5.1% respectively; Fisher's test p = 0.02)." (PMID 20386593, 2010). "However, anti-TNF therapy significantly reduced the number of total splenocytes (data not shown) and splenomegaly." (PMID 25140115, 2014). "In further support of this observation, administration of the mAb anti-TNF-α (in combination with anti-IFN-γ, or not) reduced splenomegaly in mice infected with P. chabaudi." (PMID 36093199, 2022). "Indeed, the accelerated development of splenomegaly and loss of MZM in mice lacking Blimp-1 expression in T cells was associated with disrupted cell trafficking into the spleen, which could be rescued by TNF blockade." (PMID 26765224, 2016).